APOB (apolipoprotein B)
Diseases named in the same sentence as APOB in open-access papers (continued):
Sharing a sentence is not in itself a finding about the gene and the disease.
dyslipidemia (continued). "Rather, our data shows impairment in chylomicron-apoB48, TG and remnant-C are potentially better markers of early atherogenic ApoB-dyslipidemia in young high-risk overweight-obese women with and without PCOS." (PMID 40995592, 2025). "Future research should prioritize HF populations with high residual metabolic risk, including patients with HFrEF and coexisting diabetes, HFpEF with obesity or metabolic syndrome, and individuals with persistently elevated ApoB or triglyceride-rich lipoproteins despite guideline-directed therapy." (PMID 41567901, 2025). "Consequently, ApoB has been shown to outperform LDL-C in predicting cardiovascular risk, particularly in patients with metabolic syndrome, diabetes, or discordant lipid profiles." (PMID 41388300, 2025). "The ways in which ApoB particle density is influenced by insulin resistance, nutrient status, hepatic lipid flux, inflammation, and genetic variation, all of which contribute to dyslipoproteinemic phenotypes associated with ASCVD and metabolic syndrome." (PMID 41346943, 2025). "Notably, certain metabolites such as glycoprotein acetyls, ApoB/ApoA1 ratio, and lactate emerge as promising biomarkers for insulin resistance and metabolic syndrome, suggesting their potential utility in clinical settings." (PMID 40507103, 2025). "The Framingham Offspring Study showed that LDL-p and ApoB outperformed non-HDL in predicting the risk of cardiovascular disease events in metabolic syndrome and diabetes mellitus." (PMID 39027784, 2024). "In this study, we assessed the impact of incorporating the ApoB test into traditional lipid tests through agreement analysis and by evaluating the prevalence of dyslipidemia and high ApoB using various cutoffs in Korean adults who underwent lipid testing at local clinics and hospitals." (PMID 38535329, 2024). "Combining high doses of fish oil (FO) with metformin appears to have a favorable impact on female patients with PCOS and metabolic syndrome, leading to decreased concentrations of ApoB48 and ApoB100, with beneficial effects on both fasting and postprandial serum TGs and ApoB levels." (PMID 38393015, 2024). "A total of 2629 (27.4%) were classified as having dyslipidemia based on traditional lipid tests and/or ApoB results (any), while 1682 (17.5%) were identified as high-risk for CVD solely based on elevated ApoB levels (≥100 mg/dL) as their other traditional lipid parameters were within normal ranges." (PMID 38535329, 2024). "A recent study comparing serum apolipoprotein B with retinal neurovascular structural alterations in patients with type 2 diabetes using OCTA found that individuals with dyslipidemia had significantly less vessel density and perfusion density than those with diabetes." (PMID 39598024, 2024). "In colorectal polyps, we found that significantly higher levels of TC and ApoB than non-polyp, which demonstrated that dyslipidemia possibility associated with colorectal polyp, consistent with the previous investigations." (PMID 39252808, 2024). "Additionally, patients with acute cerebral infarction who were older than 60 years, suffering from hypertensive disorders, chronic smokers, and dyslipidemia, had higher levels of ApoB/ApoA-I." (PMID 38274879, 2023). "However, according to the current Korean guidelines for dyslipidemia, ApoB is recommended as an additional biomarker in specific clinical situations, such as diabetes and familial hypercholesterolemia, without specific cutoff values." (PMID 37892015, 2023). "According to the recent ESC/ASA Guidelines for the management of dyslipidemia lipid modification to reduce cardiovascular risk, around 20% of patients may have discordance between measured LDL-C and ApoB levels." (PMID 36975891, 2023). "This could be due to an age-related increase in postprandial dyslipidemia, insulin resistance, and age-related decline in ApoB/E receptor and sex hormones (estrogen and androgen)." (PMID 37355585, 2023).
dyslipidemia (continued). "Therefore, we analyze the relationship between ApoB and eGFR decline in participants with diabetes, hypertension, dyslipidemia, and hypohemia." (PMID 37124758, 2023). "The article defines atherogenic dyslipidemia as an imbalance between ApoB and apolipoprotein AI." (PMID 38017531, 2023). "In addition, patients diagnosed with the metabolic syndrome showed significantly elevated Anti-ApoB IgG (p = 0.002)." (PMID 35479271, 2022). "In addition, the ApoB/ApoA1 ratio is now widely used to predict the occurrence of CVDs and metabolic syndrome because it is a composite index that comprehensively reflects the lipid metabolism balance." (PMID 36140721, 2022). "In this work, univariate analysis showed that the higher LDL-C, HbA1c, and ApoB and lower ApoA-I and HDL-C were significantly associated with an increased CAD risk of elderly T2DM patients, suggesting that dyslipidemia and inflammatory disorders were important risk factors of CAD." (PMID 36397150, 2022). "Furthermore, the findings of the study, with the exception of the novel loci, demonstrated the dyslipidemia-related functions of ApoA1 and ApoB/ApoA1-related genes." (PMID 36140721, 2022). "Additionally, previous studies have suggested that naringenin can improve dyslipidemia and apolipoprotein B overproduction." (PMID 35228523, 2022). "The 2019-European Society of Cardiology/European Atherosclerosis Society guidelines for the management of dyslipidemias, recommended that physicians consider measuring apoB for CVD risk assessment, particularly in patients with HTG, diabetes, obesity, metabolic syndrome, or low levels of LDL-C." (PMID 35910208, 2022). "In addition, apoB was positively correlated with hypertension and dyslipidemia, whereas apoC1 was also positively correlated with hypertension." (PMID 36551995, 2022). "Atherogenic dyslipidemia, which comprises the concurrence of increased serum triglyceride (TG), apolipoprotein B, and small dense low-density lipoprotein cholesterol (LDL-C) levels along with decreased HDL-C level, plays a major role in the genesis of atherosclerotic plaques." (PMID 34930134, 2021). "In addition, apoB is better as a target in patients with mild to moderate hypertriglyceridemia (175–880 mg/dL), diabetes, obesity or metabolic syndrome." (PMID 34677405, 2021). "Therefore, the high ApoB concentration in the NAFLD group is further evidence of dyslipidemia in these patients." (PMID 34034748, 2021). "Since it has been established that hyperuricemia is associated with dyslipidemia such as hypertriglyceridemia, variants of A1CF may affect urate metabolism via the following ApoB-related mechanisms." (PMID 33517564, 2021). "Furthermore, in people with hypertriglyceridemia, type II diabetes, or metabolic syndrome, the protective ApoA-I values are also low, creating a high and “risky” ApoB/ApoA-1 ratio value." (PMID 34952923, 2021). "The ApoB/ApoA1 ratio is a promising diagnostic tool for metabolic syndrome (MS) in different populations, though its use is not established in Kazakhstan." (PMID 32717783, 2020). "Low density lipoprotein cholesterol is considered as the main indicator of the dyslipidemia, while the serum concentrations of total cholesterol, triglyceride, high density lipoprotein cholesterol, apolipoprotein A, and apolipoprotein B are regarded as the secondary indicators." (PMID 33080674, 2020). "In this context, elevated serum apoB levels have been related to diabetes and metabolic syndrome, both of which may affect cancer development." (PMID 31936330, 2020). "The AG and AA genotypes frequency of ApoB-rs1042031 are higher in the dyslipidemia group." (PMID 30119683, 2018).
dyslipidemia (continued). "The levels of weight, percent of smoking and drinking, serum glucose, serum TC, triglyceride (TG) and LDL-C were higher, as well as the levels of serum high-density lipoprotein cholesterol (HDL-C) and the ratio of ApoA1 to ApoB were lower in dyslipidemia than in normal groups (P < 0.05–0.001)." (PMID 29670124, 2018). "And we realized that the high level of serum apoB (or apoB/apoAI ratio, which is part of metabolic syndrome) and HCY are both related to JCSLs and WMLs, suggesting they could be two stages of CSVD and JCSLs that may continue to progress if left untreated." (PMID 29018401, 2017). "The PDI-associated client protein hepatic apoB accumulated with the PDI-binding status in chronic stress, and curcumin recovered the altered ER folding status, regulating ER stress and the resultant hepatic dyslipidemia." (PMID 28747775, 2017). "Subjects with metabolic syndrome, here defined by low water T2, displayed statistically significant increases in the mean concentrations of fibrinogen, complement C3c, haptoglobin, apolipoprotein B, α1-acid glycoprotein and complement C4c, as well as total plasma proteins and globulins (black bars)." (PMID 29258604, 2017). "Researches revealed that NAR could affect dyslipidemia, apoB overproduction, and hyperinsulinemia in LDL-receptor null mice with diet-induced insulin resistance." (PMID 27446963, 2016). "Dysregulation of lipoprotein metabolism in the metabolic syndrome may be due to a combination of overproduction of very-low density lipoprotein (VLDL) ApoB, decreased catabolism of ApoB-containing particles, and increased catabolism of HDL-ApoAI particles." (PMID 25949827, 2015). "The study was designed to assess the association between insulin resistance (IR) and apolipoprotein B/apolipoprotein A-I ratio (ApoB/ApoA-I ratio), metabolic syndrome (MetS) components, total cholesterol (TC), and low-density lipoprotein cholesterol (LDL-C) in the nondiabetic population of Georgia." (PMID 24949011, 2014). "Indeed, apoB significantly and independently predicted CVD risk among post-infarction patients with metabolic syndrome." (PMID 25118169, 2014). "Therefore, our results showing decreased visceral adiposity and decreased ApoB is consistent with a protective effect of KCJ against the development of metabolic syndrome." (PMID 23442518, 2013). "Results of multivariable Cox regression demonstrated non-significance (p = 0.17) for peak versus base subjects in a model adjusted for gender, age, BMI, hypertension, metabolic syndrome, smoking, and levels of apoA-I, apoA-II, apoB, apoE, total cholesterol, CRP, HDL-C, and triglycerides." (PMID 22723940, 2012). "Emerging evidence suggests that integrating waist circumference (WC) with biochemical markers—particularly plasma triglycerides (TG) and apolipoprotein B (ApoB)—may enhance risk stratification accuracy by quantifying both abdominal adiposity topography and VAT‐associated dyslipidemia." (PMID 40825749, 2025). "Furthermore, early pregnancy levels of ApoB, and the ApoB/ApoA ratio were found to be positively associated with pre-pregnancy BMI, which is consistent with the atherogenic dyslipidemia phenotype often found in non-pregnant individuals with OWO." (PMID 39841244, 2025). "This disruption may lead to dyslipidemia, which is characterized by elevated triglycerides and low cholesterol levels, an elevated apolipoprotein B-to-apolipoprotein A1 ratio and an increase in low-density lipoprotein cholesterol, and is associated with increased blood pressure." (PMID 40391041, 2025). "Additionally, 4 genes (APOB, INSR, PPARG, APOC3) had prior genetic associations with MASLD while another 12 genes had associations with a MASLD-related phenotype (type 2 diabetes, BMI-adjusted waist-to-hip ratio (WHRadjBMI), metabolic syndrome)." (PMID 40065360, 2025).
dyslipidemia (continued). "In this study, 39.0%, 3.5%, and 0.4% of subjects who were not identified as having dyslipidemia based on traditional lipid test results were newly recognized as having a high-risk for CVD when using ApoB cutoffs of 100 mg/dL, 130 mg/dL, and 145 mg/dL, respectively." (PMID 38535329, 2024). "Given that current clinical guidelines in Korea recommend the ApoB test for specific groups like patients with diabetes mellitus and familial hypercholesterolemia, the observed differences in dyslipidemia prevalence may be influenced by the characteristics of the population studied." (PMID 38535329, 2024). "However, there is emerging evidence to suggest that dyslipidemia—including elevated levels of Lp(a) and ApoB—may contribute to inflammatory and degenerative joint conditions." (PMID 37763183, 2023). "However, the effects of APOB variants on lipid profiles, metabolic syndrome, and diabetes mellitus (DM) in Asian populations have not been fully elucidated." (PMID 36499290, 2022). "In addition, APOB variants at the 3′ intergenic region played a crucial role in increased triglyceride and remnant cholesterol levels and decreased HDL cholesterol levels; they also increased the risk of metabolic syndrome." (PMID 36499290, 2022). "Moreover, a larger prospective cohort study using WGS will be more powerful in detecting whether other functional variants are more critical genetic determinants of lipids profile and metabolic syndrome in the APOB locus." (PMID 36499290, 2022). "Also, evolocumab Q2W or QM enabled a majority of individuals at high/very-high cardiovascular disease risk to achieve the LDL-C, non-HDL-C, and ApoB goals recommended by the 2019 ESC/EAS dyslipidemia guidelines." (PMID 33941192, 2021). "CKD is associated with dyslipidemia which comprises of normal to increased low-density lipoprotein cholesterol (LDL-C) concentrations, low high-density lipoprotein cholesterol (HDL-C) levels, and elevated levels of triglycerides (TGs), and apolipoprotein B (Apo B) containing lipoproteins." (PMID 30597982, 2018). "The rs2483058C-rs2580520G haplotype was associated with an increased risk of dyslipidemia, and showed consistent association with serum total cholesterol (TC), high-density lipoprotein cholesterol (HDL-C), apolipoprotein (Apo) A1 levels, and the ApoA1/ApoB ratio." (PMID 28912560, 2017). "The present study assessed the association between the serum apoB/A-I ratio and CAC according to kidney function status in a large number of healthy subjects without a previous history of CVD or other confounding risk factors for CVD, including diabetes, hypertension, or dyslipidemia." (PMID 28957410, 2017). "Based on these findings, Sniderman and Faraj recommended that the dyslipidemia be redefined to include ApoB and ApoA-I as stronger risk marker especially compared to LDL-C (often low in MetS), TG, and HDL-C." (PMID 24949011, 2014). "However, whether apoB/apoA1 ratio is a better indicator of metabolic syndrome than other biomarkers and what is the optimal cut-off value of apoB/apoA1 ratio as an indicator of metabolic syndrome in Chinese population remain unknown." (PMID 24886173, 2014). "Mainly present in genes of lipid metabolic pathways (APOA5, APOB, APOC3 and LPL), the higher frequency of risk alleles in Puerto Ricans has been associated previously in other populations with unfavorable lipid profile and insulin response, cardiovascular conditions and metabolic syndrome." (PMID 19682384, 2009). "Additional associations have been reported with LV thickness and mass, carotid intima‐media thickness, blood pressure, uric acid, HDL‐C, apolipoprotein B and ALT in youth with obesity and features of the metabolic syndrome." (PMID 41251158, 2026). "Hepatic ApoB translation during VLDL synthesis depends on lipid availability; thus, dysregulation of intrahepatic lipid metabolism can lead to dyslipidemia." (PMID 40429957, 2025).
dyslipidemia (continued). "Age, sex, metabolic syndrome, alcohol, Smoking, education, Charlson comorbidity index, MMSE score at baseline, serum albumin, apolipoprotein B/A1 ratio." (PMID 41262081, 2025). "It treats dyslipidemia by inhibiting diacylglycerol acetyltransferase-2 (DGAT-2i), increasing acylation of fatty acids, reducing TG creation, and degrading additional ApoB, further lowering LDL levels." (PMID 40264627, 2025). "The present study found that dyslipidemia, such as TG, TC, LDL-C, ApoB, TC/HDL-C ratio, TG/HDL-C ratio, LDL-C/HDL-C ratio, and ApoB/ApoA1ratio, plays an important role in the occurrence and development of colorectal polyps." (PMID 39252808, 2024). "Furthermore, ApoB may serve as a superior measure of ASCVD in cases of metabolic syndrome." (PMID 38393015, 2024). "Among these, dyslipidemia is common, presenting as low high-density lipoprotein cholesterol (HDL-c), high triglycerides (TG), Apolipoprotein-B (Apo-B), and small dense low-density lipoprotein (sdLDL) predominance, collectively known as diabetic dyslipidemia." (PMID 39588429, 2024). "This systematic review evaluates the efficacy of recently approved drugs for dyslipidemia, including bempedoic acid, evolocumab, alirocumab, and inclisiran, in reducing LDL-C and apolipoprotein-B levels." (PMID 39439648, 2024). "Dyslipidemia observed in type 2 diabetes mellitus (T2DM) is characterized by elevated triglycerides, ApoB, and small dense low-density lipoprotein (sd-LDL) levels, along with a concurrent decrease in HDL-C, all stemming from the underlying insulin resistance." (PMID 38393015, 2024). "The concentrations of early metabolic syndrome biomarkers [adiponectin, leptin, TNF-α, IL-1, IL-6, IL-10, endothelin-1, apolipoprotein B, and lipoprotein (a)] were measured and a cardiopulmonary exercise test (CPET) was performed." (PMID 38254811, 2024). "In men, as the NAMA/TAMA quartile decreased, the ORs of dyslipidemia, according to the HDL-C, TG, sdLDL, and ApoB/A1 definitions, significantly increased." (PMID 39170735, 2024). "Nowadays, international guidelines have incorporated ApoB measurement as an alternative to the LDL-C assay, especially in subjects with very low LDL-C levels or in patients with metabolic syndrome (METs)." (PMID 38393015, 2024). "SLE patients showed a pattern of dyslipidemia and dyslipoproteinemia, characterized with the increase of serum TG, TC, LDL, and ApoB, while the decrease of serum HDL and ApoA1." (PMID 36790644, 2023). "Fifty-eight patients with a score greater than 8 were identified, of which 40 patients were excluded due to elevated APOB and/or LDL levels (>100 mg/dL), suggesting mixed dyslipidemia." (PMID 36978188, 2023). "Future studies based on detailed clinical information regarding dyslipidemia are needed to clarify the clinical implications of various equations estimating LDL-C and its relationship with ApoB." (PMID 37375689, 2023). "Other research has reported that HRW can reduce serum LDL and ApoB levels, while improving dyslipidemia-impaired high-density lipoprotein cholesterol (HDL) function and reducing oxidative stress, and may have beneficial effects on preventing underlying metabolic syndrome." (PMID 37371975, 2023). "Dyslipidemia had a higher prevalence among young female patients with SLE than among controls; this was characterized by decreased TC, LDL-c, HDL-c, ApoA, and ApoB." (PMID 35371016, 2022). "For dyslipidemia management, the ESC guideline recommended apolipoprotein B (ApoB) and low-density lipoprotein cholesterol (LDL-C) as the secondary and the primary target, respectively." (PMID 35146010, 2022). "Compared with the control group, Patients with IH had a higher degree of dyslipidemia, reflected in elevated total cholesterol (TC), triglycerides (TG), low-density lipoprotein cholesterol (LDL-C), and apolipoprotein B (Apo B) levels." (PMID 36536397, 2022).